BIRC5 (baculoviral IAP repeat containing 5)
Diseases named in the same sentence as BIRC5 in open-access papers (continued):
Sharing a sentence is not in itself a finding about the gene and the disease.
cancer (continued). "Here, we applied a pan-cancer multiomics approach in 33 different cancer types to examine molecular mechanisms that can ultimately lead to the high BIRC5 gene expression patterns observed in cancer." (PMID 35331169, 2022). "In the present study, we used publicly available -omics (genomics, transcriptomics) and survival data to examine BIRC5 genetic alterations and altered expression in 33 cancer types in relation to prognosis." (PMID 35331169, 2022). "BIRC5 is abundantly expressed in cancer tissue, particularly BC, and it has been shown to enhance cell proliferation in various malignancies." (PMID 35631261, 2022). "In agreement with previous studies, our results also show that BIRC5 expression levels are higher in cancer tissue than normal tissue." (PMID 35331169, 2022). "Though BIRC5 has been validated as a target of cancer drugs, the number of BIRC5 inhibitors available for clinical testing is limited." (PMID 35406376, 2022). "We found that BIRC5 was differentially expressed in normal and tumor samples in 32 out of the 33 cancer types provided in the TCGA database." (PMID 35886952, 2022). "We also used the GEPIA database to determine the prognostic value of BIRC family genes in LGG; among these genes, increased BIRC5 expression was correlated with worse clinical outcomes in this cancer type." (PMID 35309512, 2022). "Then, a prognostic index for all cancer was constructed by the formula MRG = expression level of BIRC5 × (−0.4126) + expression level of PLK1 × 0.39986 + expression level of CDKN3 × 0.2651 + expression level of CYP4B1 × (−0.0955)." (PMID 36293001, 2022). "Taken together, our findings demonstrate the prognostic relevance of BIRC5 expression in a variety of cancer types from different organ systems." (PMID 35331169, 2022). "Taken together, the results demonstrate that BIRC5 was correlated with sensitivity to diverse drugs from the Cancer Therapeutic Response Portal database." (PMID 35309512, 2022). "Co-targeting of BIRC5 with various other genes that have significant roles in cancer progression is another avenue that needs to be explored for developing better targeting strategies." (PMID 35886952, 2022). "These predicted effects rely in the inactivation of key transcription factors (NF-κB, c-FLIP, VEGFA, survivin or BIRC5) involved in resistance to death and inhibition of survival signals in cancer cells." (PMID 35106125, 2022). "Although the clinical outcomes of these trials remain inconclusive, enthusiasm in targeting Birc5 for cancers remains high." (PMID 35836253, 2022). "BIRC5 was also named surviving, which researchers have paid more attention to as a cancer therapy target." (PMID 36292719, 2022). "Our study suggests BIRC5 as a promising prognostic biomarker for several cancer types, but these findings need to be investigated further." (PMID 35331169, 2022). "Given that N6-methyladenosine (m6A) RNA methylation plays a major role in the initiation and progression of LGG, we examined the correlation between BIRC5 expression and regulators of m6A RNA methylation in this cancer type." (PMID 35309512, 2022). "Our findings further confirm that BIRC5 expression levels are higher in cancer than in normal tissue, which is consistent with earlier findings." (PMID 36358602, 2022). "Among TAAs, BIRC5 and EphA2 are prognostic markers and therapeutic targets in various cancers, including GBM." (PMID 36439089, 2022). "BIRC5 is overexpressed in most human cancers and is correlated with poor prognosis of patients, however, it is shows low expression levels in normal tissues." (PMID 34490029, 2021). "Previously, massive literature reports that BIRC5 is rarely expressed in normal tissues, so it has become the main target for tumor diagnosis, prognosis and anti-cancer treatment." (PMID 34112092, 2021). "BIRC5 has potential as a therapeutic target for ICB in cancer patients, and the relationship between BIRC5 and high TMB and high MSI warrants more in-depth study." (PMID 33431968, 2021).
cancer (continued). "Multiepitope cancer vaccines prepared against BIRC5 in recent years inhibit tumor growth and strongly suppress lung metastasis." (PMID 33431968, 2021). "The relationship between BIRC5 expression and the immune and stromal scores of tumors in pan-cancer patients and the infiltration level of 22 tumor-infiltrating lymphocytes (TILs) was analyzed." (PMID 33431968, 2021). "Clusters 6 and 7 (lymphH6 and lymphH7) exhibited higher levels of pro-survival/cell cycle regulation genes (BIRC5, TOP2A, CENPF) associated with metabolically active cancer pathways." (PMID 34579762, 2021). "BIRC5 is involved in many cancers, and the survivin protein has been identified as a cancer biomarker." (PMID 34289837, 2021). "As one of the well-established pro-cancer interactions of BIRC5 is its binding with the Hsp90, we now propose that it is likely that this protein–protein interaction is preserved while BIRC5 participates in the protein corona of nanocomposites." (PMID 34503306, 2021). "More and more studies suggest that the development of BIRC5 specific anti-cancer drugs is making progress." (PMID 34030694, 2021). "Bioinformatics techniques were used in this study to predict BIRC5 affects the prognosis of pan-cancer and infiltration of immune cells in tumors." (PMID 33431968, 2021). "Several clinical studies are ongoing with the therapeutic aim of inhibiting AURKB in an effort to target genes involved in the “BIRC5 cancer network” and clinical responses indicate a central role of this pathway in proliferating leukaemic cells." (PMID 34638823, 2021). "Specifically, BIRC5 is overexpressed in different human cancers as an oncogene and, thus, is a key target for anticancer therapy." (PMID 34650929, 2021). "BIRC5 was of particular interest since its expression has been identified as a cancer biomarker in many types of cancers." (PMID 34289837, 2021). "BIRC5 is a well-known therapeutic target of cancers and plays an important role in cell division and inhibits cell death." (PMID 34820377, 2021). "BIRC5, also known as Survivin plays a key role in cancer by modulating cell division and proliferation and through inhibition of apoptosis." (PMID 34490029, 2021). "The transcription levels of BIRC5 in different cancers were determined by joint analysis of pan-cancer data in TCGA matched with normal samples in GTEx." (PMID 33431968, 2021). "In conclusion, this study shows that BIRC5 can be as a biomarker for use in the diagnosis and prognosis of cancers." (PMID 33431968, 2021). "For the “Pathway in cancer” pathway, a total of 18 risk lncRNAs synergistically regulated ER (ESR1), E2F (E2F1 and E2F2), CyclinA1 (CCND1), and Survivin (BIRC5), which indirectly leads to tumor cell proliferation." (PMID 34149805, 2021). "It has been studied that the correlation between BIRC5 promoter methylation and expression is complicated in cancers." (PMID 34685742, 2021). "BIRC5 is a well-known cancer therapeutic target, and its gene promoters are frequently used for transcriptional targeting of tumor cells." (PMID 34790823, 2021). "Because BIRC5 is highly expressed in a variety of tumors, promote tumor progression, and influence immune cell status, researchers have used different means to target BIRC5 in cancer patients." (PMID 33431968, 2021). "Several cancer-associated genes have been identified on chromosome 17q, including PPM1D, EME1, BRCA1, ERBB2, NF1, RAD51C, BRIP1 and BIRC5." (PMID 34885154, 2021). "The present manuscript collects and reviews the most recent literature concerning the role played by BIRC3 and BIRC5 in cancer cells, providing useful information for the choice of the best therapeutic targets." (PMID 33413657, 2021). "In line with our results, inhibition of BIRC5-202 expression is connected to diverse aspects of cancer progression, including increased apoptosis, impaired cell migration and decreased cisplatin-resistance in GC." (PMID 34044823, 2021).
cancer (continued). "Baculoviral IAP repeat containing 5 (BIRC5) has been broadly studied among cancer therapeutic targets, and its main function is to suppress cell death." (PMID 34988121, 2021). "Analysis of expression profiling data of tumor tissues and healthy tissues of patients with different cancers in the TCGA database revealed that BIRC5 was highly expressed in 21 out of 33 tumor tissues." (PMID 33431968, 2021). "Given that immune infiltrating cells play a significant role in cancer development, we investigated the relationship between BIRC5 expression levels and immune cell infiltration in different types of cancers." (PMID 33431968, 2021). "Several recent studies presented experimental evidence for the role of BIRC5/survivin in cancer cell motility, including the melanoma model that revealed the α5-integrin pathway, cervical carcinoma, and others." (PMID 34064473, 2021). "Survivin (also known as baculoviral inhibitor of apoptosis repeat containing 5 [BIRC5]), is a member of the inhibitor of apoptosis family, and ranks highly among potential targets due to its overexpression in a wide variety of cancers." (PMID 34944889, 2021). "Sox-2 mediated upregulation of BIRC5 is important in tumour progression, apoptotic inhibition, and resistance to chemotherapy in cancers." (PMID 34685742, 2021). "Overexpression of BIRC5 was observed in about half of the pan-cancers in the Oncomine database, and NSCLC showed the greatest difference between normal and tumor tissues." (PMID 34804966, 2021). "CCNA2, CCNB1, and CCNE1 were co-expressed with BIRC5, a well-known cancer therapeutic target which directly regulates both apoptosis and mitosis in cancer cells during tumorigenesis and tumor metastasis." (PMID 33996604, 2021). "Birc5 was highly expressed in various cancers such as lung cancer, ovarian cancer, breast cancer, brain tumor, colon cancer, pancreatic cancer, osteosarcoma, and cervical cancer." (PMID 32155884, 2020). "Targeting BIRC5 including antisense oligonucleotide, ribozyme, RNA interference, and cancer vaccine in experimental models improved survival." (PMID 32043523, 2020). "Birc5 acts as inhibitor of apoptotic processes by repressing caspase activity via binding to caspase-3 and -7 in cancer cells, leading to the survival of cancer cells during tumorigenesis." (PMID 32155884, 2020). "BIRC5 (baculoviral IAP repeat containing 5) is overexpressed in various tumors and associated with poor cancer survival." (PMID 32855362, 2020). "For example, BIRC5 was significantly anti-correlated with miR-101, miR-664a, miR-29c, miR-30a, miR-125 and miR-139 expression in over 40% of the cancers." (PMID 31964418, 2020). "Based on the high activation of BIRC5 during tumorigenesis in various cancer types, treatment that targets BIRC5 has been increasingly noticed as a promising therapeutic strategy." (PMID 32043523, 2020). "The trend of relative expression (cancer vs. healthy tissues) was indeed more favourable for Survivin/BIRC5 than for TERT." (PMID 32152425, 2020). "This was consistent with previous studies demonstrating that the up-regulation of BIRC5 leads to the development and progression of many malignant tumors in humans." (PMID 33292199, 2020). "In particular, BIRC5 immunotherapy used in combination with standard therapies or with targeted precision drugs have shown great anti‐cancer potential." (PMID 32841536, 2020). "From the chart downloaded from UALCAN, baculoviral IAP repeat-containing protein 5 (survivin/BIRC5) is overexpressed in many cancers making it more possible to regulate the release of SMAC." (PMID 32325691, 2020). "Since BIRC5 is frequently overexpressed in a majority of malignancies, treatment that targets BIRC5 has been increasingly noticed as a novel strategy for various malignant tumors." (PMID 32043523, 2020).
cancer (continued). "Most types of cancer are characterized by overexpression of BIRC5; they include the following types of cancer: breast, liver, ovarian, bladder, lung, stomach, and esophageal and hematological malignancies." (PMID 30774747, 2019). "BIRC5 rs9904341 was correlated with increased expression at both mRNA and protein levels in cancer cells." (PMID 31156712, 2019). "Recently, detection of serum BIRC5 levels has been found to be positively correlated with early diagnosis of different human cancers, including breast cancer." (PMID 31530877, 2019). "The frequency of BIRC5 positive sera in cancerous dogs was significantly higher (p < 0.001) than dogs with non-cancerous diseases and healthy dogs." (PMID 31530877, 2019). "Research progress of core genes in HCC: BIRC5, also known as survivin, is an anti-apoptotic protein reported to function as a potential oncogene in the context of many cancers." (PMID 31534853, 2019). "Survivin (BIRC5, product of the BIRC5 gene) is highly expressed in many tumor types and has been widely identified as a potential target for cancer therapy." (PMID 31551409, 2019). "BIRC5 (also known as survivin) is a critical anti‐apoptotic protein that is been involved in many cancer types." (PMID 31250518, 2019). "As in the case of the previously discussed genes, increased BIRC5 overexpression characterizes most types of cancers." (PMID 31756998, 2019). "The highest frequency genes in CNGs, BIRC5, ERBB2 and EZH2 were used to perform a pan-cancer mutational analysis." (PMID 29459674, 2018). "BIRC5 agents have been identified as a potential therapeutic target in cancer treatment but their long-term effectiveness is unclear." (PMID 29459674, 2018). "Nevertheless, pirfenidone was, in part, capable in attenuating the ‘cancer-like’ phenotype of IPF-fibroblasts, through partial downregulation of the cancer-associated gene BIRC5 (survivin)." (PMID 30481203, 2018). "In spleen cells of that study, cancer-related gene Cdkn2a was found up-regulated by spaceflight, while Birc5, Casp8, Ctnnb1, Map2k1, Mdm2, Nfkb1, and Pdgfa showed less expression." (PMID 28701719, 2017). "The mechanism of YAP1-promoted resistance includes activation of the receptor tyrosine kinase AXL, the apoptosis inhibitor Survivin (BIRC5) genes, and autophagy depending on different drugs in different cancers." (PMID 27911857, 2017). "BIRC5 induced cancer cell apoptosis and cell cycle arrest, thereby efficiently inhibiting the proliferative activity in HCC." (PMID 29190974, 2017). "Introducing BIRC5 antisense oligonucleotides or BIRC5 inhibitors into cancer cells reduced BIRC5 expression in cells, inhibited cell proliferation, and lowered the cell apoptosis rate." (PMID 29190974, 2017). "Here, we analyzed the Cancer Genome Atlas to evaluate the differential expression of IAP family genes (save BIRC5 which we have studied previously) in LGG and HGG." (PMID 27074575, 2017). "Of these molecules, YM155 is one of the inhibitors targeting the BIRC5 (Survivin) gene, an anti-apoptotic factor, which is highly overexpressed in ESCs/iPSCs and cancer stem cells." (PMID 28412976, 2017). "Baculoviral IAP Repeat Containing 5 (BIRC5) is preferentially expressed in human cancer cells and mediates cancer cell survival and tumor maintenance." (PMID 29190974, 2017). "The expression levels of CDH3, IGF2BP3, HOXB7, and BIRC5 mRNA in malignant biliary strictures were significantly higher than in benign strictures (P = 0.006, <0.001, <0.001, and 0.001, respectively)." (PMID 27399126, 2016). "BIRC5 gene has the potential to be a marker for the detection and prognosis of cancer at an early age." (PMID 27372966, 2016). "BIRC5 mRNA is highly expressed in many cancers relative to differentiated tissues and thus represents an attractive target for this technology." (PMID 27203672, 2016).
cancer (continued). "ROC curve analysis for BIRC5/Survivin expression levels demonstrates marginal discriminatory power in distinguishing cancer from normal tissues with statistical significance (AUC = 0.598; 95%CI = 0.526–0.666; p = 0.015)." (PMID 27827395, 2016). "Further analysis of clinical specimens suggested that expression of KLF5 and BIRC5 is up-regulated during the progression from inflammation to cancer." (PMID 26474386, 2015). "Recent studies from other groups have shown that several microRNAs such as miR-542-3p, miR-218, miR-708 and miR-203 directly inhibited BIRC5 expression in different types of cancer." (PMID 24520312, 2014). "BIRC5 is a member of the inhibitor of apoptosis (IAP) family preferentially expressed by many cancers including BC." (PMID 24520312, 2014). "BIRC5 immunostaining was mainly localized in cancer cell cytoplasm and nuclei, and OCT4 expression was localized in cancer cell nuclei." (PMID 23433354, 2013). "OCT4 and BIRC5 are preferentially expressed in human cancer cells and mediate cancer cell survival and tumor maintenance." (PMID 23433354, 2013). "Although certain strategies for cancer therapy targeting BIRC5 have shown a varied extent of antitumor efficacy, the potential benefit of single anti-BIRC5 treatment in different types of cancers is uncertain." (PMID 23433354, 2013). "Co-suppression of OCT4 and BIRC5 induced cancer cell apoptosis and cell cycle arrest, thereby efficiently inhibiting the proliferative activity of cancer cells and suppressing the growth of HCC xenogrfts in nude mice." (PMID 23433354, 2013). "OCT4 and BIRC5 expression was also investigated by immunohistochemistry in 49 pairs of cancer and liver tissues taken from HCC patients." (PMID 23433354, 2013). "Clinical follow-up information also demonstrated that the HCC patients who showed co-expression of OCT4 and BIRC5 in cancer tissues had poorer disease-free survival (DFS) and overall survival (OS) than patients who were negative for both OCT4 and BIRC5." (PMID 23433354, 2013). "Co-suppression of OCT4 and BIRC5 further enhanced the inhibitory effect on cancer cell proliferation." (PMID 23433354, 2013). "The distinct increase in the fold change in BIRC5 expression was statistically significant in both cancer cell lines compared to the control HUVEC cells." (PMID 24037645, 2013). "Based on the abnormally high activation of BIRC5 during carcinogenesis in various types of cancers, treatment that targets BIRC5 has been increasingly recognized as a promising therapy for various cancers." (PMID 23433354, 2013). "Survivin (BIRC5), a member of the inhibitor of apoptosis protein (IAP) family that inhibits caspases and blocks cell death is highly expressed in cancer and is associated with a poorer clinical outcome." (PMID 21470426, 2011). "BIRC5, also known as survivin, is an inhibitor of apoptosis that has been shown to be highly expressed in the majority of cancers, including soft tissue sarcomas and osteosarcomas." (PMID 18522746, 2008). "In the TCGA-LIHC cohort, the expression levels and risk scores of STC2 and BIRC5 were positively correlated with the expression level of PDL1, indicated that both STC2 and BIRC5 can promote the expression of PDL1 on cancer cells, thereby promoting tumor immune escape." (PMID 40458412, 2025). "Compared with the normal group, GCA, ANXA6, and BIRC5 in the cancer group were increased." (PMID 40616392, 2025). "However, certain SEGs such as BIRC5 are differentially expressed in cancer, supporting the idea that context-dependent perturbations can confer unexpected specificity—likely contributing to the SEG panel’s moderate performance." (PMID 41045509, 2025).